ANKRD46 (ankyrin repeat domain 46)
Synonyms: ANK-S; GENX-115279
Tractability: Antibody: UniProt predicts a signal peptide or a membrane-spanning region. PROTAC: ubiquitination databases record sites on it; its protein half-life has been measured.
Gene: Protein-coding gene on chromosome 8 (100,509,752 to 100,559,784, reverse strand). Ensembl gene ENSG00000186106.
Subcellular location: Membrane
Subcellular location (Human Protein Atlas): Cytosol
Gene Ontology:
Cellular component: membrane
Genetic constraint (gnomAD): Loss-of-function variants: 12 observed, 20.14 expected, observed/expected ratio (o/e) 0.6, 90% interval 0.38 to 0.96. The upper end of that interval is the gene's LOEUF score, 0.96, which puts it in group 4 of 6, group 1 being the genes least tolerant of losing a copy. Missense variants: 185 observed, 284.09 expected, observed/expected ratio (o/e) 0.65, 90% interval 0.58 to 0.74. Synonymous variants: 91 observed, 112.22 expected, observed/expected ratio (o/e) 0.81, 90% interval 0.68 to 0.96.
Homologues: Orthologues: guinea pig ANKRD46 (100% identical), pig ANKRD46 (100% identical), mouse Ankrd46 (98% identical), tropical clawed frog ankrd46 (96% identical), rabbit ANKRD46 (94% identical), macaque ANKRD46 (94% identical), chimpanzee ANKRD46 (93% identical), rat Ankrd46 (93% identical), zebrafish ankrd46a (73% identical), zebrafish ankrd46b (73% identical).
Diseases named in the same sentence as ANKRD46 in open-access papers:
ANKRD46 is named in the same sentence as 8 diseases in open-access papers, as found by Europe PMC text mining. Sharing a sentence is not in itself a finding about the gene and the disease. The quoted sentences say what the papers report.
breast carcinoma (2 papers, 2011 to 2023). "Through the literature search, we found that there were few studies on the ANKRD46 gene, which mainly plays a pathogenic role in tumors, such as nasopharyngeal carcinoma, breast cancer, and gastric cancer." (PMID 37189611, 2023). "Luciferase assays using a reporter carrying a putative target site in the 3' untranslated region of ANKRD46 revealed that miR-21 directly targeted ANKRD46. miR-21 and EIF4A2 protein were inversely expressed in breast cancers (rs = -0.283, P = 0.005, Spearman's correlation analysis)." (PMID 21219636, 2011).
cancer (1 paper, 2011). A tumor composed of atypical neoplastic, often pleomorphic cells that invade other tissues. "Two candidate target genes (EIF4A2 and ANKRD46) were selected for analysis of correlation with clinicopathological characteristics and prognosis using immunohistochemistry on cancer tissue microrrays." (PMID 21219636, 2011).
myopathies (1 paper, 2020). "The last downregulated gene is ANKRD46 whose function is not known, particularly in connection with myopathies." (PMID 32670085, 2020).
ANKRD46 also shares sentences with these, for which no sentence is quoted: diabetes (1 paper); gastric cancer (1); nasopharyngeal carcinoma (1); nicotine dependence (1); postmenopausal osteoporosis (1).